CHRM3 (cholinergic receptor muscarinic 3)
Diseases named in the same sentence as CHRM3 in open-access papers (continued):
Sharing a sentence is not in itself a finding about the gene and the disease.
cancer (21 papers, 2013 to 2025). A tumor composed of atypical neoplastic, often pleomorphic cells that invade other tissues. "Compared to adjacent normal colon, CHRM3 expression was increased up to 128-fold in 10 of 18 consecutive surgical cancer specimens (56%) and associated with metastatic spread (P < 0.05)." (PMID 28416748, 2017). "In mice, functional M3R deficiency, whether achieved by ablating Chrm3 or more recently by selective M3R antagonism, reduces tumor number and attenuates cancer cell invasion." (PMID 35370785, 2022). "Totally 8 SNPs in 3 genes, COMT, HTR3B, CHRM3 (rs1176744, rs3782025, rs1672717, rs165722, rs4680, rs4633, rs10802789, rs685550), were significantly associated with the interindividual differences in nausea and vomiting among cancer patients treated with opioids." (PMID 23766564, 2013). "Transcriptome analysis revealed that CHRM3 knockdown significantly reduced an array of classic factors involved in cancer invasive growth, including MMP1/MMP3/MMP10/MMP12 and CXCL1/CXCL5/CXCL8." (PMID 37744266, 2023). "Transcriptome analysis revealed that CHRM3 knockdown significantly reduced an array of classic factors in cancer invasive growth including MMP1/MMP3/MMP10/MMP12 and CXCL1/CXCL5/CXCL8." (PMID 37744266, 2023). "Comparing muscarinic receptor subtype expression levels in adenocarcinoma vs. normal colon samples, we consistently observed reduced CHRM1, CHRM2, and CHRM4 and increased CHRM3 RNA levels (log2fc normal relative to cancer tissue)." (PMID 35370785, 2022). "Controlling the false discovery rate at 5%, ECAR selected six genes CHRM3, CTCFL, KCNE2, MLANA, MSMP, TTLL2, many of which have been reported to be associated with lung function or cancer." (PMID 34857823, 2021). "Compared to normal colon, we observed robust MMP1 mRNA over-expression in 16 of the 18 cancer specimens (89%), but we were unable to identify a quantitative relationship between CHRM3 and MMP1 expression levels." (PMID 28416748, 2017). "Moreover, CHRM3 stimulated GBM development by upregulating an array of classic factors in cancer cells invasive growth." (PMID 37744266, 2023). "Overall, the Chrms, especially the Chrm1 and Chrm3, appear as promising targets for cancer therapy." (PMID 32477953, 2020). "However, specific regulation mechanisms between CHRM3 and those classic factors involved in cancer invasive growth in GBM cells remain unclear." (PMID 37744266, 2023).
adenocarcinoma (7 papers, 2013 to 2025). A common cancer characterized by the presence of malignant glandular cells. "Compared to normal colon, median ARHGEF7 and CHRM3 transcript levels were higher in adenocarcinomas [21.734 vs. 18.244 per million for ARHGEF7 (p = 1.3962E-10); 2.528 vs. 1.272 for CHRM3 (p = 0.00236)]." (PMID 37805544, 2023). "We compared relative ARHGEF7 and CHRM3 mRNA expression in 17 fresh human adenocarcinomas and paired normal colon." (PMID 37805544, 2023). "Conversely, the 76% reduction in adenocarcinomas in colons from Chrm3-/- compared to WT mice was highly significant (P < 0.001)." (PMID 24694019, 2014). "In the present study, we found that CHRM3 was highly expressed in the SCLC-SCC cell line NCI-H520 and moderately expressed in the adenocarcinoma cell lines A549 and NCI-H1299." (PMID 40718823, 2025). "Consistent with this, here we found that CHRM3 was highly expressed in the SCLC-SCC cell line NCI-H520 and moderately expressed in the adenocarcinoma cell lines A549 and NCI-H1299." (PMID 40718823, 2025).
Bacterial Infection (2 papers, 2015 to 2022). "Chrm3 deficiency in mice significantly abrogates the ability to launch an effective adaptive immune response to helminth and bacterial infections." (PMID 35870560, 2022).
infection (2 papers, 2017 to 2025). The state of being infected such as from the introduction of a foreign agent such as serum, vaccine, antigenic substance or organism. "After infection, the expression of CHRM3 was determined using RT-qPCR and western blot assays." (PMID 40718823, 2025).
CHRM3 also shares sentences with these, for which no sentence is quoted: glioblastoma (4 papers); anhidrosis (3); developmental delay (3); emphysema (3); Obesity (3); airway hyperresponsiveness (2); Anxiety (2); bipolar disorder (2); cardiac diseases (2); cardiac hypertrophy (2); Cardiovascular Diseases (2); cholangiocarcinoma (2); melanoma (2); metastatic disease (2); pemphigus (2); rheumatoid arthritis (2); alcohol dependence (1); alopecia (1); atherosclerosis (1); autism (1); basal cell carcinoma (1); cervical cancer (1); chronic asthma (1); chronic obstructive pulmonary disease (1); CNS tumors (1); colorectal adenoma (1); congenital lower urinary tract obstruction (1); COVID-19 (1); cryptorchidism (1); cystitis (1).
A further 28 diseases each share a sentence with CHRM3 in 1 paper.